OSTN (osteocrin)
Description:
Hormone that acts as a regulator of dendritic growth in the developing cerebral cortex in response to sensory experience. Induced in the brain following membrane depolarization and inhibits dendritic branching in neurons of the developing cortex. Probably acts by binding to natriuretic peptide receptor NPR3/NPR-C, thereby preventing binding between NPR3/NPR-C and natriuretic peptides, leading to increase cGMP production (By similarity).
Synonyms: MUSCLIN
Tractability: Antibody: UniProt places it where antibodies can reach, with high confidence; UniProt predicts a signal peptide or a membrane-spanning region; its Gene Ontology location is reachable by antibodies, with medium confidence.
Gene: Protein-coding gene on chromosome 3 (191,199,241 to 191,265,615, forward strand). Ensembl gene ENSG00000188729.
Subcellular location: Secreted
Gene Ontology:
Molecular function: hormone activity; signaling receptor binding
Biological process: bone growth; negative regulation of dendrite extension; hormone-mediated signaling pathway
Cellular component: extracellular region
Genetic constraint (gnomAD): Loss-of-function variants: 6 observed, 8.05 expected, observed/expected ratio (o/e) 0.75, 90% interval 0.41 to 1.46. That is too few expected variants to judge how well the gene tolerates losing a copy. Missense variants: 117 observed, 123.35 expected, observed/expected ratio (o/e) 0.95, 90% interval 0.82 to 1.11. Synonymous variants: 41 observed, 44.28 expected, observed/expected ratio (o/e) 0.93, 90% interval 0.72 to 1.2.
Homologues: Orthologues: chimpanzee OSTN (99% identical), macaque OSTN (99% identical), dog OSTN (89% identical), pig OSTN (86% identical), rabbit OSTN (86% identical), guinea pig OSTN (83% identical), rat Ostn (77% identical), mouse Ostn (74% identical), tropical clawed frog ostn (63% identical), zebrafish ostn (45% identical).
Diseases named in the same sentence as OSTN in open-access papers:
OSTN is named in the same sentence as 19 diseases in open-access papers, as found by Europe PMC text mining. Sharing a sentence is not in itself a finding about the gene and the disease. The quoted sentences say what the papers report.
myocardial infarction (4 papers, 2019 to 2023). Gross necrosis of the myocardium, as a result of interruption of the blood supply to the area, as in coronary thrombosis. "Recent findings from us and other laboratories have validated the cardioprotective role of OSTN in mice with myocardial infarction or doxorubicin insult." (PMID 34135313, 2021). "Furthermore, a recent study found that OSTN treatment notably suppressed heart failure and cardiac rupture in mice after myocardial infarction." (PMID 32618439, 2020). "Inspiringly, OSTN was also reported to be abundant in the myocardium that functioned as a therapeutic agent against cardiac rupture and congestive heart failure in mice after myocardial infarction." (PMID 32618439, 2020). "In addition, transgenic mice overexpressing osteocrin (OSTN-Tg) have an improved prognosis and higher survival rates after myocardial infarction (MI)." (PMID 31072047, 2019).
heart failure (3 papers, 2021 to 2024). Inability of the heart to pump blood at an adequate rate to meet tissue metabolic requirements. "Osteocrin is a molecule released when performing physical activity which improves neuronal function, bone development, and physical endurance, prevents inflammatory signaling, cardiac rupture, and heart failure." (PMID 34746212, 2021). "Collectively, these findings point to potentially important roles of OSTN in cardiovascular, muscle and adipose tissues, which need to be explored further using appropriate stressors in experimental animal models of pathological conditions, such as heart failure or obesity." (PMID 38890799, 2024).
type 2 diabetes (3 papers, 2021 to 2023). "Of note, STZ injection simply imitates the symptoms of type 1 diabetes in the clinic (e.g., polydipsia, polyphagia, and weight loss); however, whether OSTN can also protect against cardiac dysfunction in a different diabetic model, such as high fat diet-induced type 2 diabetes, remains unclear." (PMID 34135313, 2021). "Both MUP‐1 and OSTN are shown to be related to insulin sensitivity in an inverse way in type 2 diabetic rodent models." (PMID 37170065, 2023).
diabetes (2 papers, 2021 to 2022). "Taken together, these findings indicate that OSTN overexpression attenuates diabetes-caused cardiomyocyte apoptosis and fibrotic remodeling, thereby preventing cardiac dysfunction in mice." (PMID 34135313, 2021). "As expected, BZM administration abrogated the beneficial effects of OSTN on diabetes-related cell apoptosis and fibrotic remodeling." (PMID 34135313, 2021). "OSTN reduction in diabetic hearts prompted us to explore whether OSTN overexpression could prevent diabetes-related cardiac injury and dysfunction." (PMID 34135313, 2021). "Three weeks after diabetes induction, mice received a single tail-vein injection of the cardiotropic AAV9 vectors to specifically overexpress OSTN in the myocardium." (PMID 34135313, 2021). "Meanwhile, OSTN overexpression failed to prevent diabetes-related cardiac dysfunction in CFZ-treated mice." (PMID 34135313, 2021). "Accordingly, cardiac-specific overexpression of OSTN did not affect body weight, food uptake, water consumption, and FBG levels, but resulted in a significant improvement of diabetes-related cardiac dysfunction." (PMID 34135313, 2021).
Cachexia (1 paper, 2022). Severe weight loss, wasting of muscle, loss of appetite, and general debility related to a chronic disease. "To investigate whether or not our findings might also be relevant in patients, we assessed OSTN mRNA levels in vastus lateralis muscle biopsy specimens from control individuals and from patients with sarcopenia or cachexia due to CHF." (PMID 35013221, 2022). "Therapeutic overexpression of Musclin in skeletal muscle might also be beneficial in patients: Musclin (OSTN) mRNA levels in skeletal muscle biopsies from patients suffering from heart failure and sarcopenia or cachexia were markedly downregulated." (PMID 35013221, 2022).
diabetic cardiomyopathy (1 paper, 2021). Diabetic cardiomyopathy is a disorder of the heart muscle in people with diabetes. "Herein, we aim to investigate the role and underlying molecular basis of OSTN in diabetic cardiomyopathy (DCM)." (PMID 34135313, 2021).
minimal change nephropathy (1 paper, 2021). "To investigate the role of OSTN in podocyte injury, we used ADR nephropathy model, which presents with massive proteinuria similar to human minimal change nephropathy." (PMID 34750411, 2021).
type 1 diabetes (1 paper, 2021). "Consistently, we herein detected a decreased cardiac OSTN expression in STZ-induced type 1 diabetes with lower insulin levels." (PMID 34135313, 2021).
cardiac diseases (2 papers, 2018 to 2021). "Osteocrin (OSTN) acts as a novel exercise-responsive myokine and is implicated in various cardiac diseases." (PMID 34135313, 2021).
cancer (1 paper, 2020). A tumor composed of atypical neoplastic, often pleomorphic cells that invade other tissues. "Collectively, OSTN could be a promising cardioprotective factor for cancer patients exposed to DOX treatment or suffered to cachexia." (PMID 32618439, 2020).
infection (1 paper, 2020). The state of being infected such as from the introduction of a foreign agent such as serum, vaccine, antigenic substance or organism. "Cells with siOstn infection had a significant decrease of OSTN protein level." (PMID 32618439, 2020).
nervous system diseases (1 paper, 2019). "Furthermore, the osteocrin-derived peptide 128 (Osteocrin33-50) shares disease associations with GPR68, spanning cardiovascular, eye, genetic, immune system, metabolic, and nervous system diseases." (PMID 31675498, 2019).
OSTN also shares sentences with these, for which no sentence is quoted: Insulin resistance (3 papers); Alzheimer disease (2); Obesity (2); congestive heart failure (1); Myocardial fibrosis (1); Polydipsia (1); sarcopenia (1).